GALNT2 (polypeptide N-acetylgalactosaminyltransferase 2)
Diseases named in the same sentence as GALNT2 in open-access papers (continued):
Sharing a sentence is not in itself a finding about the gene and the disease.
gastric cancer (6 papers, 2012 to 2023). A primary or metastatic malignant neoplasm involving the stomach. "In summary, GALNT2 is frequently downregulated in advanced gastric cancer, and lower GALNT2 expression is associated with poor disease-free survival." (PMID 26848976, 2016). "The effects of GALNT2 on gastric cancer cells and the underlying mechanisms were studied using in vitro and in vivo experiments." (PMID 26848976, 2016). "Further studies of the molecular mechanisms underlying the effects of GALNT2 in gastric cancer would be helpful." (PMID 26848976, 2016). "In addition, in human gastric cancer cells, high GALNT2 expression is associated with remarkable inhibition of growth and metastasis." (PMID 28025493, 2016). "Additionally, our in vitro results were similar to a previous study in that GALNT2 knockdown was associated with increased cell proliferation, adhesion, and invasion in gastric cancer cells." (PMID 26848976, 2016). "In contrast, our previous reports showed that GALNT2 knockdown enhanced their activity in gastric cancer cells." (PMID 36409270, 2023). "Knockdown of GALNT2 in gastric cancer cells resulted in decreased Tn antigen and increased phosphorylation of EGFR." (PMID 34069424, 2021). "In this study, we first examined the expression of GALNT2 in gastric cancer and its correlation with clinicopathological features." (PMID 26848976, 2016). "GALNT2 knockdown in gastric cancer reduced Tn antigen expression on MET, as evidenced by reduced VVA binding." (PMID 26848976, 2016). "GALNT2 downregulation promoted malignant phenotypes in gastric cancer, including cell proliferation, migration, invasion, and tumor metastasis, by increasing MET phosphorylation." (PMID 26848976, 2016). "AGS cells and cells from the MKN45 gastric cancer line, which had relatively low GALNT2 expression, were transfected with pcDNA3.1(+)-GALNT2 plasmid to overexpress GALNT2." (PMID 26848976, 2016). "Here, we showed that downregulation of GALNT2 also correlated with increased malignant progression in gastric cancer." (PMID 26848976, 2016). "To investigate the role of GALNT2 in gastric cancer, we first analyzed GALNT2 expression in 5 gastric cancer cell lines and in GES-1 cells using Western blotting." (PMID 26848976, 2016). "Second, increased phosphorylation of other RTKs, including EGFR, was also shown in GALNT2 knockdown gastric cancer cells." (PMID 26848976, 2016). "Knockdown of GALNT2 enhanced malignant phenotypes in gastric cancer cells and promoted tumor metastasis in a nude mouse model." (PMID 26848976, 2016). "A MET inhibitor, PHA665752, reversed the effects of GALNT2 knockdown on gastric cancer cell survival, invasion, and migration, suggesting that GALNT2 affects GC progression by modifying MET activity." (PMID 26848976, 2016). "To better understand the molecular mechanisms by which GALNT2 gene expression affects gastric cancer progression, we evaluated global gene expression changes in control and GALNT2-knockdown AGS cells." (PMID 26848976, 2016). "These in vitro experiments showed that GALNT2 downregulation might promote malignant progression in gastric cancer." (PMID 26848976, 2016). "Whether GALNT2 also suppresses EGF-induced phenotypes in gastric cancer cells requires further study." (PMID 26848976, 2016). "Furthermore, GALNT2 expression is downregulated in gastric cancer." (PMID 34069424, 2021). "Additionally, GALNT2 expression was downregulated in more advanced gastric cancer (**p < 0.005)." (PMID 26848976, 2016). "Furthermore, we showed that GALNT2 can modify MET O-glycosylation in gastric cancer cells." (PMID 26848976, 2016). "IHC staining of GALNT2 and MET was performed in gastric cancer tissues, and IHC scores for GALNT2 and MET staining were correlated using a linear regression model." (PMID 26848976, 2016). "First, the signaling pathways leading to increased proliferation, invasion, and migration in GALNT-2 knockdown gastric cancer cells were not explored in our study." (PMID 26848976, 2016).
gastric cancer (continued). "In these gastric cancer cases, the expression of circ-hnRNPU, NONO, or c-Myc was negatively or positively correlated with that of target genes GALNT2, GALNT6, MGAT1, or hnRNPU." (PMID 37993881, 2023). "Importantly, as a RBP, cytoplasmic NONO stabilizes GALNT2, GALNT6, and hnRNPU mRNA in gastric cancer cells, which is also repressed by circ-hnRNPU." (PMID 37993881, 2023).
colorectal cancer (5 papers, 2014 to 2025). A primary or metastatic malignant neoplasm that affects the colon or rectum. "Among 20 GALNT members, GALNT2 is consistently associated with poor survival of patients with colorectal cancer in public databases." (PMID 36409270, 2023). "Data retrieved from the Human Protein Atlas and Kaplan–Meier Plotter indicated that, among 20 GALNT enzymes, only GALNT2 mRNA levels are significantly associated with poor survival of patients with colorectal cancer in both databases." (PMID 36409270, 2023). "Kaplan–Meier analysis showed that overexpression of GALNT2 is associated with poorer overall survival of patients with colorectal cancer." (PMID 36409270, 2023). "Kaplan–Meier survival curves using TCGA dataset in the Human Protein Atlas showed that high GALNT2 expression is associated with poor survival of patients with colorectal cancer." (PMID 36409270, 2023). "GALNT2 overexpression was associated with poor survival of colorectal cancer patients." (PMID 36409270, 2023). "For example, in colorectal cancer, GALNT2 modifies the O-glycosylation of the AXL receptor tyrosine kinase, thereby regulating AXL levels and promoting tumor invasion." (PMID 40861802, 2025). "GALNT2 has been shown to contribute to the enhanced aggressiveness of colorectal cancer cells, doing so in part by modulating the AXL pathway." (PMID 38596689, 2024). "The information gained from this study provides novel insights into the role of GALNT2‐AXL axis in the pathogenesis of colorectal cancer progression." (PMID 36409270, 2023). "We, therefore, proposed that GALNT2‐mediated invasiveness of colorectal cancer is at least partly through AXL." (PMID 36409270, 2023). "Forced expression of GALNT2 promoted migration and invasion as well as peritoneal metastasis of colorectal cancer cells." (PMID 36409270, 2023). "We, therefore, focused on the investigation of the clinical significance of GALNT2 in colorectal cancer." (PMID 36409270, 2023). "In this study, we focused on GALNT2, the best GALNT gene associated with poor survival of colorectal cancer patients in public databases." (PMID 36409270, 2023). "Because we and others have ever found that GALNT2 could regulate EGFR and MET phosphorylation which have been demonstrated to modulate colorectal cancer metastasis, we tested if GALNT2 knockout could interfere with their signaling." (PMID 36409270, 2023). "Although we have found that GALNT2 plays either tumor‐suppressive or tumor‐promoting role in several cancer types, its pathophysiologic functions in colorectal cancer remain unclear." (PMID 36409270, 2023). "The abundance of GALNT1 and GALNT2 has been found to be significantly higher in colorectal cancer than that in normal epithelium, and high GALNT3 protein expression has been reported to be an indicator of tumor differentiation and a prognostic factor in colorectal cancer." (PMID 35692787, 2022).
coronary heart disease (5 papers, 2013 to 2023). "GALNT2 plays important roles in lipid homeostasis, and differential methylation of the GALNT2 locus in humans is associated with coronary heart disease, and with sex differences in cardiometabolic diseases." (PMID 36668811, 2023). "One study shows that promoter methylation of GALNT2 is associated with a higher risk of coronary heart disease." (PMID 30275900, 2018). "Of note, however, GALNT2 rs2144300 (previously associated with high-density lipoprotein cholesterol levels in EA) had multiple potentially novel PheWAS associations, with hypertension related phenotypes in AA and with serum calcium levels and coronary artery disease phenotypes in EA." (PMID 23382687, 2013).
diabetes (5 papers, 2017 to 2024). "This association needs to be further investigated to understand in depth its role in mediating the effect of GALNT2 on insulin sensitivity, glucose control and other clinical features in people with diabetes." (PMID 38627282, 2024). "Downregulation of GALNT2 was involved in abnormal glucose metabolism in diabetes." (PMID 35368875, 2022).
Intellectual disability (5 papers, 2021 to 2025). "Interestingly, in patients, GALNT2’s loss of function causes a neurodevelopmental disorder with global developmental delay, intellectual disability with language deficit, autistic features, and behavioral abnormalities." (PMID 39859496, 2025). "Novel congenital disorders with global development delay, intellectual disability and decreased HDL-C caused by GALNT2 deficiency in humans have recently been reported, and these multiple phenotypes also occur in Galnt2-deficient rodent models." (PMID 34576978, 2021). "Symptoms include intellectual disability, epilepsy, insomnia, and brain MRI abnormalities, and rodent models of Galnt2 knockout also displayed neurologic abnormalities consistent with a functional role of Galnt2-mediated glycosylation in the brain." (PMID 35022400, 2022). "Furthermore, two cases of human homozygous LOF mutations in hepatic GALNT2 with low levels of HDL-C and moderate reduction of TG in plasma were recently reported while searching for causes of heritable neurological traits and intellectual disability." (PMID 34576978, 2021). "Similarly, those with GALNT2-CDG exhibit diverse neurological abnormalities, including intellectual disability, epilepsy, and white matter changes on brain MRI." (PMID 41008563, 2025).
Hyperglycemia (4 papers, 2013 to 2022). An increased concentration of glucose in the blood. "The biology underlying these associations (e.g., is GALNT2 down-regulation causing hyperglycemia or, vice versa, is hyperglycemia causing GALNT2 down-regulation)?" (PMID 35055114, 2022). "Since GALNT2 down-regulation causes cellular insulin resistance, it could be hypothesized that it plays a central role on hyperglycemia-induced insulin resistance (i.e. glucose toxicity)." (PMID 23894607, 2013). "In conclusion, presently available in vivo data in both humans and rodents clearly indicate that GALNT2 is down-regulated in insulin resistant diabetic individuals and suggest, together with in vitro data, that such an association is, at least partly, secondary to hyperglycemia." (PMID 23894607, 2013). "To get deeper insights about the relationship between hyperglycemia and GALNT2 down-regulation observed in human PWBC, we evaluated in vitro the effect of high glucose concentrations on GALNT2 mRNA levels in cultured human U937 monocytes." (PMID 23894607, 2013).
Insulin resistance (4 papers, 2013 to 2024). Increased resistance towards insulin, that is, diminished effectiveness of insulin in reducing blood glucose levels. "A role of GALNT2 in modulating insulin sensitivity is also suggested by preliminary genetic studies indicating that GALNT2 variability is associated with HOMA-insulin resistance index in women with polycystic ovary syndrome." (PMID 35055114, 2022). "Moreover, the decreased GALNT2 expression has been associated with insulin resistance and atherogenic dyslipidemia." (PMID 39541108, 2024).
cervical cancer (3 papers, 2022 to 2023). A primary or metastatic malignant neoplasm involving the cervix. "GALNT2 was associated with worse overall survival and could be utilized as a prognostic biomarker for cervical cancer." (PMID 37650946, 2023). "To explore the potential oncogenic pathways by which GALNT2 are involved in cervical cancer, we used GSEA to analyze the correlation between GALNT2 expression and oncogenic pathways." (PMID 36110252, 2022). "Public databases and our immunohistochemistry staining demonstrated that GALNT2 expression was increased in cervical cancer compared with normal cervix tissues." (PMID 36110252, 2022). "Then we analyzed other GEO databases, and showed that GALNT2 was increased in cervical cancer samples (GSE7803, GSE6791, GSE7410)." (PMID 36110252, 2022). "The mRNA expression and protein level of GALNT2 was upregulated in cervical high-grade intraepithelial neoplasia and cervical cancer tissues." (PMID 36110252, 2022). "As GALNT2 is the most altered glycosyltransferase, we chose GALNT2 as the target gene and tried to explore the role of GALNT2 in cervical cancer." (PMID 36110252, 2022). "Here, we found that GALNT2 was upregulated in cervical cancer not only by using bioinformatic analysis, but also by using immunohistochemistry in different pathological types of cervical tissue." (PMID 36110252, 2022). "In current study, we showed the expression pattern and prognostic value of O-glycosylating enzyme GALNT2 in cervical cancer." (PMID 36110252, 2022). "Compared with normal cervix tissues, the expressions of several glycosyltransferases in cervical cancer tissues were upregulated, including GALNT2, POGLUT1, EXT1, B3GAT3, B4GALNT1 and UGT8 (GSE9750)." (PMID 36110252, 2022). "Collectively, our findings indicate that GALNT2 might be used as a potential prognostic biomarker for cervical cancer." (PMID 36110252, 2022). "Importantly, GALNT2 affected the prognostic assessment of immune modulatory molecules in cervical cancer patients." (PMID 36110252, 2022). "Here, we focus on the expression pattern of mucin glycosylating enzyme GALNT2 in cervical cancer." (PMID 36110252, 2022). "In addition, GSEA analysis showed that various immune-related pathways were closely related to the expression of GALNT2 in cervical cancer." (PMID 36110252, 2022). "Our analysis suggested that GALNT2 might be a potential unfavorable factor in cervical cancer." (PMID 36110252, 2022). "However, the expression pattern of GALNT2 in cervical cancer is still unclear." (PMID 36110252, 2022). "In conclusion, our study revealed that the mRNA expression and the protein level of GALNT2 were increased in cervical cancer, and concomitant high expressions of GALNT2 and specific cytokines, chemokines or immune modulatory molecules could predicte patients’ unfavorable survival in cervical cancer." (PMID 36110252, 2022).
congenital disorder of glycosylation (3 papers, 2022 to 2025). Congenital disorder of glycosylation (CDG) is a fast growing group of inborn errors of metabolism characterized by defective activity of enzymes that participate in glycosylation (modification of proteins and other macromolecules by adding and processing of oligosaccharide side chains). "Recently, human GALNT2 deficiency was presented as a syndromic disorder called GALNT2-congenital disorder of glycosylation (GALNT2-CDG)." (PMID 35304331, 2022). "For instance, in GALNT2-related congenital disorders of glycosylation (GALNT2-CDG), patients commonly present with phenotypes involving neurodevelopmental delay, autistic traits, hypotonia, and cerebellar dysfunction, while animal models show deficits in motor and sensory integration." (PMID 40870030, 2025).
developmental delay (3 papers, 2022 to 2025). "Furthermore, GALNT2-CDG patients not only exhibit reduced levels of plasma HDL cholesterol and triglycerides, but also dysmorphic facial features, short stature and developmental delay." (PMID 35304331, 2022).
gastric adenocarcinoma (3 papers, 2016 to 2022). "Collectively, these data revealed that GALNT2 expression is downregulated in advanced gastric adenocarcinoma and that reduced GALNT2 is associated with poorer prognosis." (PMID 26848976, 2016). "GALNT2 was downregulated in gastric adenocarcinoma, and lower GALNT2 expression correlated with more advanced tumor stage, lymph node metastasis, and reduced disease-free survival." (PMID 26848976, 2016). "Here, we report that N- acetylgalactosaminyltransferase 2 (GALNT2), an enzyme that mediates the initial step of mucin type-O glycosylation, suppresses malignant phenotypes in gastric adenocarcinoma (GCA) by modifying MET (Hepatocyte growth factor receptor) activity." (PMID 26848976, 2016).
Hypertension (3 papers, 2013 to 2022). The presence of chronic increased pressure in the systemic arterial system. "Of these genes, A2ML1, AGGF1, CBS, ECE1, GABRB3, GALNT2, MRPS6/SLC5A3, and SPG7 had documented associations with hypertension, ischemic stroke and methionine metabolism, atherosclerosis, and early-onset MI." (PMID 34252155, 2021).
lung adenocarcinoma (3 papers, 2022 to 2023). A carcinoma that arises from the lung and is characterized by the presence of malignant glandular epithelial cells. "In lung adenocarcinoma, GALNT2 was found to regulate the proliferation and mobility of cancer cells via activating the Notch/Hes1-PTEN-PI3K/Akt axis." (PMID 36110252, 2022). "Similarly, the methylation level of GALNT2/14 was negatively correlated with its expression, and patients with GALNT2/14 hypomethylation had shorter OS in lung adenocarcinoma." (PMID 36777735, 2023). "Several recent independent studies revealed that GALNT2 was overexpressed in lung adenocarcinoma." (PMID 36058918, 2022).
oral squamous cell carcinoma (3 papers, 2017 to 2022). "GALNT2 contributes to malignant behaviors of oral squamous cell carcinoma." (PMID 28388560, 2017).
Alzheimer disease (2 papers, 2018). A progressive, neurodegenerative disease characterized by loss of function and death of nerve cells in several areas of the brain leading to loss of cognitive function such as memory and language. "It is interesting to note that GALNT2 rs4846835 was associated with dementia and core Alzheimer’s disease neuropathologic changes, albeit not at the genome-wide level." (PMID 30255811, 2018).
glioblastoma (2 papers, 2021 to 2024). The most malignant astrocytic tumor (WHO grade IV). "Elevated GALNT2 levels are linked to unfavorable outcomes in patients with glioblastoma multiforme (GBM)." (PMID 38596689, 2024).
hypercholesterolaemia (2 papers, 2016 to 2022). "In addition, it is known that GALNT2, LPA, SCARB1, and APOC1 are genes responsible for a hereditary form of hypercholesterolemia." (PMID 35203469, 2022).
intraepithelial neoplasia (2 papers, 2022 to 2023). A precancerous neoplastic process that affects the squamous, glandular, or transitional cell epithelium without evidence of invasion. "In this study, we demonstrated that the mRNA expression and protein level of GALNT2 were increased in cervical high-grade intraepithelial neoplasia and tumor tissues compared with normal cervix tissues." (PMID 36110252, 2022).
nicotine dependence (2 papers, 2014 to 2017). Physical and psychological dependence on nicotine. "Of particular interest were findings in FRMD4A, ATP9A, GALNT2, and MEG3—genes that are implicated in processes related to nicotine dependence, smoking cessation, and placental and embryonic development." (PMID 24906187, 2014).
non-small cell lung carcinoma (2 papers, 2022 to 2023). A group of at least three distinct histological types of lung cancer, including non-small cell squamous cell carcinoma, adenocarcinoma, and large cell carcinoma. "In non-small cell lung cancer, GALNT2 modifies the O-glycosylation of integrin α5 to activate signal pathways essential for tumorigenesis and aggressiveness." (PMID 37993881, 2023).